ATR (ATR checkpoint kinase)
Diseases named in the same sentence as ATR in open-access papers (continued):
Sharing a sentence is not in itself a finding about the gene and the disease.
bladder cancer (continued). "Subsequently, we aimed to show whether DNA-PK and ATR inhibition could radiosensitize bladder cancer cells." (PMID 35740300, 2022). "As bladder cancer cells are considerably resistant to apoptosis induction under many conditions, we are characterizing these cellular effects and molecular mechanisms using the ATR inhibitor AZD6738." (PMID 35413091, 2022). "Similarly, inhibition of ATR by siRNA significantly increased the level of cisplatin-DNA adducts in bladder cancer cells." (PMID 33224881, 2020). "Furthermore, higher levels of chromatin-binding Cdc6 and ATR were detected in CDDP-resistant bladder cancer cells than in the parent bladder cancer cells." (PMID 27246979, 2016). "Treatment with WYC0209 inhibited cisplatin-induced ATR-Chk1 activation in bladder cancer cells." (PMID 26657501, 2016). "Given our finding that ATR was associated with a poor prognosis and that WYC0209 can enhance cisplatin-induced DNA damage in bladder cancer cells promote us to test whether inhibition of ATR-Chk1 pathway with WYC0209 can alter cell susceptibility to cisplatin." (PMID 26657501, 2016). "We then determined whether WYC0209 inhibited the activation of ATR-Chk1 selectively in bladder cancer cells; thus, strategies capable of inhibiting the DNA damage responses (DDRs) may be effective in muscle-invasive bladder cancer." (PMID 26657501, 2016). "Therefore, restoring the expression of downregulated miRNAs that target ATR, such as miR-27a-3p, miR-143, and miR-205, may enhance cisplatin efficacy and represent a promising strategy to overcome chemoresistance in advanced bladder cancer." (PMID 40940866, 2025). "To date, the impact of DNA-PK and ATR inhibition on bladder cancer cells has remained unknown." (PMID 35740300, 2022). "Therefore, targeting ATR-Chk1 pathway may be of great therapeutic value for cisplatin-resistant bladder cancer." (PMID 27246979, 2016). "Therefore, we speculate that inhibition of Cdc6 may enhance the sensitivity of CDDP-resistant bladder cancer cells by disturbing the ATR checkpoint signal." (PMID 27246979, 2016). "Therefore, we hypothesize that in CDDP-resistant bladder cancer cell, more ATR bind to the damaged DNA." (PMID 27246979, 2016). "After querying drug sensitivity data of over 4500 drugs in 24 bladder cancer cell lines from the DepMap database, we found that cells with less STAG2 mRNA expression are more sensitive to ATR and CHK inhibition." (PMID 40025053, 2025). "Based on the data retrieved in this study, we found that the ATR inhibitor AZD6738 can enhance the cytotoxic effects induced by gemcitabine, a ribonucleotide reductase inhibitor, in bladder cancer cells." (PMID 35413091, 2022). "Subsequently, selective inhibition of the DNA-PK and ATR pathways by AZD7648 and Ceralasertib treatment was confirmed in bladder cancer cell lines." (PMID 35740300, 2022). "Our data revealed an effective radiosensitization of invasive bladder cancer cells of various subtypes, including SCC-like, by individual and dual DNA-PK and ATR inhibition." (PMID 35740300, 2022). "Interestingly, analysis of the dataset (GSE13507) showed that ATR mRNA expression correlated with overall survival in the patients treating with chemotherapy, suggesting that high ATR expression could serve as a marker for sensitivity to cisplatin in patients with bladder cancer." (PMID 26657501, 2016). "Applying DNA-PK (AZD7648) and ATR (Ceralasertib) inhibitors on SCaBER, J82 and VMCUB-1 bladder cancer cell lines, we revealed sensitization upon ionizing radiation (IR), i.e., the IC50 for each drug shifted to a lower drug concentration with increased IR doses." (PMID 35740300, 2022). "Novel classes of inhibitors targeting DDR pathways, such as DN-PK and ATR, are currently being assessed in the early phases of clinical trials but have not yet been tested in bladder cancer." (PMID 35740300, 2022).
bladder cancer (continued). "Considering the deficiency of G1 phase checkpoint in cancer cells and the important roles of Cdc6 and ATR in chemo-resistant cancer cells, Cdc6 may be a potential specific therapeutic target for bladder cancer, especially for CDDP-resistant bladder cancer." (PMID 27246979, 2016). "Given that ATR knockdown suppresses p-glycoprotein expression, cisplatin and WYC0209 combination may be useful for treating bladder cancer." (PMID 26657501, 2016). "To define the events proximal to DNA damage that might contribute to the immunomodulatory effects of cisplatin versus carboplatin, we treated 5637 bladder cancer cells with increasing concentrations of the platinum drugs and probed the impact on DNA damage transducers ATM and ATR." (PMID 38280376, 2024).
breast tumor (11 papers, 2018 to 2025). "While, for instance, efficacy of PARP inhibitors was largely restricted to HR-deficient ovarian and breast tumors recent studies proposed also a synergistic impact of ATR inhibitors to overcome PARP inhibitor resistance." (PMID 41387887, 2025). "Furthermore, ATR-deficient fibroblasts enhanced tumor growth and aggressiveness in orthotopic breast tumor xenografts." (PMID 30410668, 2018). "In the current study, we comprehensive investigated ATM, ATR and MYC expressions at the transcriptional levels (n = 1950) and at the protein level (n = 1650) breast tumours." (PMID 30746633, 2019). "Further analysis of tryptophan metabolism, ATR, sirtuins, and PARP pathway signaling could provide a better understanding of DNA repair kinetics in PIKTOR treated breast tumors." (PMID 37491309, 2023). "Each inhibitor was studied in MCF7 breast tumor cells over a range that included concentrations previously shown to be pharmacologically active (10 μM KU55933 [ATM], 0.4 μM rucaparib [PARP], and 1 μM VE-821 [ATR])." (PMID 31581151, 2020).
head and neck squamous cell carcinoma (11 papers, 2018 to 2026). A squamous cell carcinoma that arises from any of the following anatomic sites: lip and oral cavity, nasal cavity, paranasal sinuses, pharynx, larynx, and salivary glands. "Activation of the Ataxia telangiectasia and Rad3-related (ATR) pathway is an important DNA damage response mechanism in head and neck squamous cell carcinoma (HNSCC)." (PMID 37934325, 2023). "Somatic mutations of ATM and ATR were associated with higher HRD in BLCA, LUAD, CRC, PRAD, head–neck squamous cell carcinoma (HNSC), BRCA, and kidney renal clear cell carcinoma (KIRC) (FDR < 0.008)." (PMID 34572800, 2021). "Another study explored the effects of inhibiting ATM or ATR in conjunction with RT on head and neck squamous cell carcinoma (HNSCC)." (PMID 40565309, 2025). "For instance, ATR inhibition by ceralasertib promotes sensitization to cisplatin in head and neck squamous cell carcinoma (HNSCC) regardless of presence of HPV, one of the important causes of oropharyngeal infection." (PMID 38279263, 2024).
Ataxia (10 papers, 2010 to 2025). Ataxia refers to impaired coordination of voluntary muscle movement. "Phenotypic ataxia associated with ATR loss has been described as a consequence of stem cell depletion resulting in progressive loss of Purkinje neurons in the cerebellum." (PMID 39951537, 2025). "This possibility is enhanced by strong links of ataxias to mutations in DNA damage response pathways, including ATR and ATM and our observations that the DNA damage response regulates ZASC1:ZBTB2 interaction." (PMID 33635925, 2021). "Interestingly, the authors circumstantially link the mcm2DENQ phenotypes to those of a specific MEC1 (yeast ataxia telangiectasia and Rad3 related (ATR)) allele based on the role of ATR in replication stress signaling and the phenotypic similarity with the mec1-4 allele." (PMID 28098815, 2017). "Here we show that ATR deletion in postmitotic neurons does not compromise brain development and formation; rather it enhances intrinsic neuronal activity resulting in aberrant firing and an increased epileptiform activity, which increases the susceptibility of ataxia and epilepsy in mice." (PMID 34210973, 2021). "However, Atr-PCΔ mice show ataxia due to a defect of intrinsic neuronal activity mediated by modulating presynaptic firing through interacting between ATR and synaptotagmin 2 (SYT2), rather than cerebellar degeneration." (PMID 35153719, 2021).
head and neck cancer (10 papers, 2015 to 2025). A primary or metastatic malignant neoplasm affecting the head and neck. "Moreover, ATR mutations were associated with high HRD scores in head and neck cancer and kidney cancer." (PMID 34572800, 2021). "While germline ATR mutations have not yet been reported, ATR was recently found to be downregulated in head and neck cancers and mutations within the FAT domain were observed in oropharyngeal-tumor tissue." (PMID 25954303, 2015). "Specifically, HPV+ head and neck cancers have increased levels of pCHK1, FANCD2, BRCA1, RAD51, and γH2AX foci, implying the presence of increased DSBs and activation of the ATR pathway in human tumors." (PMID 38730612, 2024). "However, ATR inhibition did not increase radiation sensitivity in HPV+ compared to HPV- head and neck cancer cells, implying there may be other DDR pathways that can substitute for the loss of ATR." (PMID 38730612, 2024).
hepatocellular carcinoma (10 papers, 2018 to 2025). A malignant tumor that arises from hepatocytes. "ATR inhibitors and anti-PD-1 immunotherapy have been associated with radiotherapy in hepatocellular carcinoma and CRC preclinical models." (PMID 40139833, 2025). "Liver-specific knockout of murine Bruce impaired ATR activation in the liver and exacerbated hepatic inflammation, fibrosis and hepatocellular carcinoma, initiated by hepatocarcinogen and genotoxin Diethylnitrosamine (DEN)." (PMID 31091257, 2019). "Based on RT-qPCR analysis of Orox A-treated hepatocellular carcinoma cells, significant increases in the mRNA transcript levels of NEIL1, OGG1, ATR, and ATM were observed." (PMID 41009509, 2025).
multiple myeloma (10 papers, 2016 to 2025). "ATM and ATR alterations (mutations and deletions) occur in a small subset of myeloma patients, respectively 4.3% and 1.5% of newly diagnosed patients." (PMID 29163849, 2017). "Notably, multiple myeloma (MM), a malignant and generally incurable disorder of mature plasma cells, has been shown to be particularly susceptible to replication stress and ATR inhibition." (PMID 37126127, 2023). "When ATR inhibition is combined with an oxygen-radicals inducer, such as piperlongumine, it is possible to selectively target the subset of multiple myeloma presenting high levels of RS." (PMID 34201047, 2021). "In multiple myeloma, ATR activity is necessary to compensate MYC-induced RS and its inhibition triggers apoptosis." (PMID 34201047, 2021). "Inhibiting DDR components, like PARP, ATR, WEE1, CHK1/2, ATM, and DNA-PKs, is under evaluation in early-phase studies for multiple myeloma and other hematological malignancies showing promising preliminary signals of activity." (PMID 41155462, 2025). "The goal of this study was to characterize the relationship between ATR and STAT3 interactions in human multiple myeloma (MM) cells." (PMID 37126127, 2023). "Our unpublished experiments indicate that endogenous ATR is also efficiently activated in extracts prepared from different cell lines, including HEK293, U2OS, and multiple myeloma cell lines." (PMID 30456359, 2018).
serous ovarian cancer (10 papers, 2020 to 2025). "Targeting the ATR-mediated RSR is particularly relevant to high-grade serous ovarian cancers (HGSOCs), which commonly exhibit molecular alterations associated with increased RS." (PMID 34552099, 2021). "Furthermore, a randomized phase 2 study in platinum-resistant high-grade serous ovarian cancer patients showed that addition of the ATR inhibitor berzosertib to gemcitabine provided benefits in terms of progression-free survival." (PMID 38812026, 2024). "Additionally, the combination of AZD6738 (ATR inhibitor) and olaparib (inhibitor of PARP (Poly ADP-ribose polymerase)) reduced tumor burden in BRCA-mutant high grade serous ovarian cancer although other study showed ARID1A loss is associated with PARP inhibitor resistance." (PMID 37087441, 2023). "In a trial of patients with high grade serous ovarian cancer (HGSOC), addition of the ATR inhibitor berzosertib to gemcitabine improved progression free survival (PFS) compared to gemcitabine alone but biomarkers predictive of treatment are lacking." (PMID 34552099, 2021).
anemia (9 papers, 2016 to 2025). A reduction in the number of red blood cells, the amount of hemoglobin, and/or the volume of packed red blood cells. "One of the most common and clinically significant adverse effects of ATR inhibition is reversible anemia, which appears to be a class effect." (PMID 40869030, 2025). "CDK12 is involved in the DNA-damage repair (DDR) pathway by regulating the expression of several DDR machinery components, including BRCA1, ATM, ATR, and Fanconi anemia (FANC) genes." (PMID 40148269, 2025). "The simultaneous administration of the PARP inhibitor olaparib with the ATR inhibitor ceralasertib, for instance, has been correlated with the onset of anemia, neutropenia, and thrombocytopenia." (PMID 38097586, 2023). "The most frequent adverse effects related to ATR and CHK1/2 inhibitors are anemia, thrombocytopenia, and neutropenia, which are also common with chemotherapy administration." (PMID 38539474, 2024). "These include the two HR factors CtIP and RAD51, the early transductors of RS signaling ATR (ataxia telangiectasia and Rad3-related) and ATRIP (ATR interacting protein), and the Fanconi anemia (FA) protein FANCD2 (Fanconi anemia group D2 protein)." (PMID 29206178, 2017). "Thus, similar to a recent report analyzing Fanconi anemia complementation group I (FANCI), ATR-mediated WRN phosphorylation is somehow involved in the suppression of dormant origin firing upon replication stress." (PMID 26695548, 2016).
chronic lymphocytic leukemia (9 papers, 2015 to 2023). "Another study reported that inhibition of ATR is effective against cancer cells in ATM-defective chronic lymphocytic leukemia." (PMID 36765693, 2023). "In this regard, it has been reported that in ATM-defective chronic lymphocytic leukemia cells, inhibition of ATR signaling by AZD6738 leads to an accumulation of unrepaired DNA damage that results in cell death by mitotic catastrophe." (PMID 28580318, 2017). "Many diseases, including ataxia telangiectasia (AT), chronic lymphocytic leukemia (CLL), and colorectal cancer (CRC) are associated with mutations in ATM28, 29, leaving ATR as the primary mediator of repair." (PMID 26310312, 2015).
acute lymphoblastic leukemia (8 papers, 2010 to 2024). Leukemia with an acute onset, characterized by the presence of lymphoblasts in the bone marrow and the peripheral blood. "Our studies revealed that ISAE induces G2/M arrest in the T cell acute lymphoblastic leukemia cell line—Jurkat cells, and stimulates the ATR/CHK1/Wee1/CDC25C signaling pathway." (PMID 38195460, 2024). "The ATM/ATR pathway has been shown to be activated by CX-5461 in acute lymphoblastic leukemia cells." (PMID 33963218, 2021). "Quantification of nucleotide biosynthesis in ATR-inhibited acute lymphoblastic leukemia (ALL) cells reveals substantial remaining de novo and salvage activities, and could not eliminate the disease in vivo." (PMID 28808226, 2017). "Reports show that T‐cell acute lymphoblastic leukemia (T‐ALL) cell lines and xenografts are sensitive to inhibitors of ATR, CHK1, and Wee1." (PMID 35510955, 2022).
brain tumors (7 papers, 2019 to 2024). "Further investigation of the concept of ATR inhibition for treatment of brain tumours, especially in vivo with brain penetrant compounds, is needed to validate these findings." (PMID 38227740, 2024). "Inhibition of ATR in the context of irradiating brain tumors has been less well studied." (PMID 35158967, 2022). "Besides PRUNE_1, the other five genes (i.e., KIF11, KIF14, ASPM, CDK6, and ATR) have been reported as mutated in hereditary MCPH and overexpressed in primary brain tumors (e.g., MB)." (PMID 34745995, 2021). "To determine whether ATRi could inhibit ATR activity in brain tumors, we induced ATR signaling with TMZ after systemic administration of ATRi." (PMID 31266951, 2019). "Here, we discuss preclinical progress in molecular targeting of ATM, ATR, CHK1, CHK2, and WEE1, checkpoint kinases in the treatment of brain tumors, and review current clinical phase I-II trials." (PMID 35158967, 2022). "In this review, we summarize the knowledge in the field of brain tumor treatment with radiation therapy and cell cycle checkpoint inhibition via targeting ATM, ATR, CHK1, CHK2, and WEE1 kinases." (PMID 35158967, 2022). "In the following, the current knowledge of the effect of inhibition of ATM, ATR, CHK1, CHK2, and WEE1 kinases regarding the radiation treatment of brain tumors will be presented." (PMID 35158967, 2022). "Inhibition of ATR and poly (ADP-ribose) polymerase (PARP) showed a synergistic effect on the viability of GBM cells, as well as on the survival of the treated animals carrying orthotopic brain tumors." (PMID 35158967, 2022). "In fact, olaparib is blood brain barrier (BBB) penetrant and could serve as an effective brain tumor therapy Considering the genomic instability of CGNPs following PARP1 and ATR ablation, there is also a potential for synergism between PARP and ATR inhibition." (PMID 35747808, 2022). "The treatment of malignant brain tumor cells by IR increased the phosphorylation of ATM and Chk2, but not that of ATR." (PMID 39273420, 2024).
medulloblastoma (7 papers, 2012 to 2022). A malignant, invasive embryonal neoplasm arising from the cerebellum. "Moreover, our data show that the inhibition of ERβ leads to enhanced ATR/Chk1 phosphorylation and the expected transition from G2/M to G1 cell cycle arrest, which was associated with better survival of medulloblastoma cells in the presence of cisplatin." (PMID 22439007, 2012). "In some cases, concomitant inhibition of both CHK1 and ATR improves therapeutic efficacy as in high-risk medulloblastomas, where high MYC levels were associated with hypersensitivity to pharmacological inhibition of either CHK1 or ATR." (PMID 34201047, 2021). "Considering the results of cell culture experiments in the context of the immunohistochemistry on clinical specimens, we conclude that human medulloblastomas show signs of endogenous replication stress including chronic ATR‐Chk1 activation and formation of the 53BP1 bodies." (PMID 28383788, 2017). "In human medulloblastoma cells, the DNA damage response was accompanied by activation of both ATR/Chk1, which is activated in response to DNA damage other than double strand breaks, including replication stress, and ATM/Chk2, which is activated predominantly in response to double strand breaks." (PMID 29234490, 2017). "To examine more closely the impact of CHK1 inhibition on DDR proteins we evaluated levels of phosphorylated ATR and ATM and phosphorylated CHK1 in medulloblastoma cells." (PMID 27449089, 2016).